VCP (valosin containing protein)
Diseases named in the same sentence as VCP in open-access papers (continued):
Sharing a sentence is not in itself a finding about the gene and the disease.
myopathy (continued). "Whilst FOXO1 inhibition enhanced the myogenic program in both ALS and VCP-myopathy myoblasts, particularly in VCP-myopathy with a 2.75-fold increase in the differentiation index, we did not observe mislocalization of FOXO1 to the nucleus or a negative impact on myogenesis." (PMID 39283487, 2024). "Third, we did not obtain muscle function tests of the patients when the MRI was performed, and therefore, the correlations made here were only done with the ambulatory status limiting the validation of MRI as an outcome measure that correlates with muscle function in VCP-MSP disease myopathy." (PMID 37603075, 2023). "Patients with VCP mutations who do not currently have symptoms of myopathy, and family members who are at risk, should be screened for signs of muscle weakness via standardized strength and functional testing by a multidisciplinary team." (PMID 35093159, 2022). "Further genetic sequencing revealed missense VUS in the glycogen phosphorylase, muscle associated (PYGM) gene (c.580C>T) and tropomyosin 2 (TPM2) gene (c.536C>T), in addition to a missense pathogenic mutation in the valosin containing protein (VCP) gene, confirming the diagnosis of VCP myopathy." (PMID 33567613, 2021). "Valosin-containing protein (VCP) is another gene that lies on this spectrum of ALS to myopathy." (PMID 30563574, 2018). "It was observed that, when ATG5 was knocked out, muscle pathology was normal, but when VCP was knocked out, there were abnormalities typical of MSP myopathies including rimmed vacuoles." (PMID 38891822, 2024). "Based on our results, the large majority of MSP and MSP‐like muscle biopsies showed myopathy with rimmed vacuoles, including 77% of VCP‐MSP, which is much more than previously reported (40%) in prior VCP‐MSP cohort." (PMID 36861178, 2023). "VCP was increased by 139.7%, HDAC6 by 98.6%, p62 by 124.8% and NBR1 by 149.2% (P<0.05) in GNE myopathy patients." (PMID 23472144, 2013). "This assumption is further supported by the fact that in VCP–related myopathy, VCP forms sarcoplasmic and myonuclear inclusions in IBMPFD patient tissue and the observation of cytoplasmic VCP increase in mutant fibroblasts as identified by our immunofluorescence studies." (PMID 36289705, 2022). "Myopathy with onset in adulthood is extensively heterogeneous with a low likelihood of obtaining any genetic diagnosis; therefore, isolated myopathy on its own would not suggest a high likelihood of identifying VCP-MSP." (PMID 35741724, 2022).
infection (31 papers, 2008 to 2025). The state of being infected such as from the introduction of a foreign agent such as serum, vaccine, antigenic substance or organism. "Finally, genetic ablation of VCP in the neutrophil and macrophage compartment rendered the mice highly susceptible to infection by Candida albicans, an observation also phenocopied by administering the VCP inhibitor." (PMID 39471181, 2024). "For example during infection, virus could use VCP to hijack ER or mitochondria-associated degradation, proteasome, or UPS modulating functions." (PMID 31636613, 2019). "In the Flaviviridae family, particularly the Flavivirus genus, VCP plays a pivotal role during early infection stages." (PMID 41288382, 2025). "VCP has been involved in numerous viral contexts, particularly those within the Flaviviridae family; these positive-sense RNA viruses exploit VCP during early stages of infection." (PMID 41288382, 2025). "Studies indicate that VCP inhibition at different time points during infection with the human coronaviruses HCoV-229E and HCoV-OC43 resulted in reduced levels of RNA replication." (PMID 39519185, 2024). "This demonstrates that VCP regulates the hantavirus dissemination to neighboring cells during the course of infection." (PMID 38190410, 2024). "We demonstrated that VCP binds to the hantavirus glycoprotein Gn before its incorporation into assembled virions and facilitates viral spread to neighboring cells during infection." (PMID 38190410, 2024). "The way viruses likely utilize VCP during the initial stages of infection has been best described in the family Flaviridae, whose cell entry is mediated by clathrin- and dynamin-dependent endocytosis." (PMID 39519185, 2024). "Briefly, HUVECs infected with lentiviruses expressing either SNV NP or GFP were lysed 48 hours post-infection and cell lysates were examined to monitor the VCP protein and mRNA expression levels." (PMID 38190410, 2024). "The impact of VCP function in the late stage of infection during viral release was studied using the Rift Valley Fever virus (RVFV)." (PMID 39519185, 2024). "Specifically, we added the VCP/p97 inhibitor CB-5083 at 1 μM to HeLa-H1 cells either 1 h before infection, following infection, or 2 h post-infection, when binding, entry, and uncoating are complete." (PMID 35615506, 2022). "Despite its impact on viral homeostasis, little is known of VCP/p97’s role during in vivo infection." (PMID 36456548, 2022). "Collectively, these studies indicate that VCP is a key cellular node targeted by viruses during infection and suggest that VCP is an attractive therapeutic target for the development of new antiviral compounds." (PMID 36196920, 2022). "VCP was shown to have multiple roles during HCMV infection since p97 inhibition at 24 h post-infection also inhibited viral production." (PMID 34578461, 2021). "By using gene silencing and pharmacological approaches to dissect ZIKV-TER94/VCP interactions, we were able to show how vital these interactions are in establishing infection in both mosquito and human cells." (PMID 33986255, 2021). "Experiments with WNV virus-like particles (VLPs) encoding a reporter gene revealed inhibition of early steps of infection with small interfering RNAs (siRNAs) specific for VCP." (PMID 34578461, 2021). "We found that this role is conserved between mosquito and human cells and that TER94/VCP is needed during the early stages of infection." (PMID 33986255, 2021). "We assume that VCP-UPP acts on ZIKV early during the infection of A549 cells, similar to what has been observed with TER94 in AF5 cells." (PMID 33986255, 2021). "Further assessment of cells subjected to KD conditions and low MOI infection revealed cells with KD VCP or TMED10 displayed defective cell proliferation and altered cell morphology." (PMID 32910773, 2020).
infection (continued). "Reduction of VCP protein levels was verified by western blot assays at 48 h (time of infection) and 64 h post-siRNA transfection (16 h post infection, time of supernatant collection)." (PMID 31636613, 2019). "In cells expressing UL148 (i148HA), we observed that calnexin, HRD1, EDEM1, and VCP colocalized with UL148 at prominent globular structures reminiscent of those observed during infection." (PMID 31822584, 2019). "We next used immunoprecipitation and western blot analysis to determine whether VCP interacts with any viral components during the course of infection." (PMID 38190410, 2024). "A disrupted replication process due to VCP inhibition has been observed in the case of infection with viruses of the Togaviridae family, including Chikunguya virus (CHIKV), Semliki Forest virus (SFV), and o’nyong’nyong virus (ONNV), or in case of flavivirus, Zika virus." (PMID 39519185, 2024). "Additionally, considerable evidence shows that VCP is vital for the escape of many viruses from organellar compartments like the ER and endosomes during infection." (PMID 36196920, 2022). "In contrast, two days post-infection, VCP distribution was drastically altered." (PMID 34696522, 2021). "However, the endoplasmic reticulum (ER)-associated degradation (ERAD) components, N-glycanase 1 (NGLY1), and valosin-containing protein (VCP) were identified as host-supportive factors that facilitate EV-A71 infection and replication." (PMID 33381104, 2020). "In order to assess if this effect was restricted to the CHIKV viral isolate used in the previous experiments, CB-5083 was used to assess the role of VCP during infection with different CHIKV isolates as well as the closely related ONNV, and more distantly related SFV all belonging to the SFV clade." (PMID 31636613, 2019). "The association of VCP with the viral replication compartments early in infection suggests that the nuclear functions of VCP may be playing a critical role in HCMV replication." (PMID 28494016, 2017). "In an intradermal infection model, mice infected with a VCP-knockout strain of vaccinia virus had increased numbers of CD4+ and CD8+ T cells at the site of infection, and exhibited increased T-dependent antibody response, compared to infection with the wild-type virus." (PMID 28197139, 2017). "Using this assay, we show that genetic ablation of TRIM21 or chemical inhibition of either the AAA ATPase p97/valosin-containing protein (VCP) or the proteasome results in a >1,000-fold increase in the relative level of infection in the presence of immune serum." (PMID 23596308, 2013). "This suggests the involvement of VCP in the acidification of the environment for envelope–membrane fusion and in the reprocessing and degradation of the nucleocapsid protein, which may indicate an important role for VCP in the infection of all coronaviruses." (PMID 39519185, 2024). "Moreover, VCP knockdown impeded viral spread to neighboring cells during the course of infection." (PMID 38190410, 2024). "However, we cannot exclude that VCP inhibition prior to infection could also result in lower trafficking of viral receptor or other entry factors." (PMID 31636613, 2019). "HPV progression from benign to transforming infection is characterized by an increase of HPV E6/E7 mRNA and protein expression, and VCP has been shown to be regulated by the HPV E6 gene through the E6-E6AP-PTPN3 network." (PMID 26934314, 2016). "VCP has previously been shown to play a role in Vpu-dependent CD4 degradation, but it is likely to impact the VSV-G pseudotyped HIV single-cycle infection used here through a separate mechanism." (PMID 24817247, 2014). "The results showed that at 12 hours post-infection (hpi), there was no observable co-localization between Core and VCP." (PMID 41288382, 2025). "VCP facilitates this uncoating process by promoting endosomal maturation; its depletion restricts virus particles to early endosomes, thereby impairing CSFV uncoating and subsequent infection." (PMID 41288382, 2025).
infection (continued). "Cells were harvested six days post infection and cell lysates were immunoprecipitated using either anti-VCP antibody or IgG as negative control." (PMID 38190410, 2024). "Recruitment of total ubiquitin, p97/VCP, ANKRD13A, and UBXD1 at 2 h was determined at the PV in cells pre-stimulated with IFNγ and then treated for 2 h with the E1 enzyme inhibitor, PYR41, prior to infection with Tg type II Pru." (PMID 37975677, 2023). "For instance, we have recently shown that VCP ATPase inhibition-mediated CM destabilization stimulates ZIKV-induced apoptosis, supporting that CMs delay cytopathic effects potentially to maximize viral replication at the late time point of infection." (PMID 34696522, 2021). "Similarly, during infection of the recombinant SINV mCherry.capsid, the virus capsid redistributed with YBX1 and TIA1 and also with VCP and G3BP1 into a single perinuclear granule." (PMID 31905741, 2019). "However, a marginal increase in the viral spread was observed in VCP knockdown HUVECs up to 6 days pos-infection without further spread up to 9 days post-infection." (PMID 38190410, 2024). "Considering this “chicken and egg” situation, an infection-based approach with longer drug treatments was not appropriate to challenge the hypothesis that VCP is involved in VP biogenesis." (PMID 34696522, 2021). "DBeQ and NMS-873 potently inhibited Nluc expression after infection with YFVΔSK/Nluc virus particles but did not inhibit Nluc expression after transfection of YFVΔSK/Nluc RNA, indicating that VCP/p97 is necessary for YFV entry, prior to the delivery and translation of incoming YFV genomes." (PMID 32291299, 2020). "Furthermore, in contrast to VCP knockdown, IE2 and pp52 expression could be detected four days post infection following Ganciclovir treatment." (PMID 28494016, 2017). "Analysis of GFP fluorescence at 48 hours post infection (HPI) indicated that all cells were infected, demonstrating that VCP expression is not required for virus entry, translocation of genome to the nucleus or initial transcription of the viral genome." (PMID 28494016, 2017). "Although we do not yet fully understand the detailed mechanism of TER94/VCP interaction with capsid and the role of UPP proteins, including UBR5, our data provide further proof that ubiquitination of viral proteins is essential during infection." (PMID 33986255, 2021).
neurological disorders (10 papers, 2016 to 2023). "Later, whole exome sequencing further revealed that VCP is associated with other neurological disorders, including familial ALS, ASD, and HSP." (PMID 29310658, 2018). "VCP, also known as P97, is one of the genes controlling protein homeostasis and is also associated with neurological disorders." (PMID 26984393, 2016). "It is unclear why mutations in a single gene, VCP, result in various neurological disorders." (PMID 29310658, 2018). "Previous studies have shown that VCP can stabilize Beclin 1 in neurological diseases and promote the progression of autophagy." (PMID 37269429, 2023). "Valosin containing protein (VCP) is a protein involved in ER biogenesis and maintenance, whose gene mutations have been linked to several neurological disorders, including ALS." (PMID 34830115, 2021). "Our former study demonstrates that Bap31 regulates one of the central nervous system disease-related gene (valosin-containing protein, VCP) expression." (PMID 32426368, 2020). "In module-5, VCP shown interaction with 5 proteins (AKTI, CAV1, HSPA8, DNM1L, TKT) functionally associated with enzyme binding processes and most of these genes are mostly related to neoplasms disorder followed by nervous system diseases." (PMID 34918006, 2022). "Because VCP and ATL1 are the causative genes of several neurodegenerative and neurodevelopmental disorders, we suggest that impaired ER formation and inefficient protein synthesis are significant in the pathogenesis of multiple neurological disorders." (PMID 26984393, 2016). "Interestingly, mutations in genes involved in the regulation of ER biogenesis and maintenance, such as Valosin-containing protein (VCP), Atlastin-1 (ATL1), Spastin (SPAST), Reticulon 2 (RTN2), and Receptor expression enhancing protein 1 (REEP1) have been linked to neurological diseases." (PMID 29310658, 2018). "Many genes play an important role, with TARDBP, SQSTM1, VCP, FUS, TBK1, CHCHD10, and most importantly, C9orf72 being critical genetic players in these neurological disorders." (PMID 33805659, 2021). "TARDBP, SQSTM1, VCP, FUS, TBK1, CHCHD10, and most importantly C9orf72, are the critical genetic players in these neurological disorders." (PMID 32116499, 2020).
autosomal dominant disease (5 papers, 2017 to 2025). Autosomal dominant form of disease. "Missense mutations of valosin-containing protein (VCP) cause an autosomal dominant disease known as inclusion body myopathy, Paget disease with frontotemporal dementia (IBMPFD) and other neurodegenerative disorders." (PMID 28322724, 2017). "MSP-1 is an autosomal dominant disease that results from mutations in VCP." (PMID 34160014, 2021). "Missense mutations of VCP lead to the autosomal dominant disease IBMPFD." (PMID 28322724, 2017). "Valosin‐containing protein (VCP) related disease, also known as multisystem proteinopathy 1 (MSP1), is an autosomal dominant disease caused by gain‐of‐function pathogenic variants of the VCP gene." (PMID 41355735, 2025).
cardiac disease (4 papers, 2016 to 2024). "Despite this, cardiac disease due to VCP variants is described only in limited series or cases." (PMID 38891822, 2024). "Valosin-containing protein (VCP) has recently been proposed to protect against cardiac diseases." (PMID 35369356, 2022). "Furthermore, recent studies also found that VCP participates in cardiomyocyte growth and survival, and plays a protective role against the stress-induced pathogenesis in heart diseases by attenuating mitochondrial and ER stress through regulating calcium homeostasis." (PMID 32481679, 2020).
neuromuscular disease (3 papers, 2021 to 2025). "VCP disease, also known as multisystem proteinopathy, is a rare, autosomal dominant, adult-onset, neuromuscular disease that is caused by variants in the valosin-containing protein (VCP) gene." (PMID 40229738, 2025).
peripheral neuropathy (3 papers, 2020 to 2025). A disorder affecting the peripheral nervous system. "Increasing the sample size of the cohort to include statistically significant data in VCP genotype–phenotype comparisons can help to analyze the progression in participants with other comorbidities such as ALS, PDB, and peripheral neuropathy." (PMID 40229738, 2025).
bacterial infection (2 papers, 2020 to 2022). "During immune defensive response against viral or bacterial infection, TRIM21 triggers pathogen neutralization by mediating UPS and valosin-containing protein (VCP, a molecular unfoldase) to eliminate such pathogens." (PMID 32984318, 2020).
cardiovascular disease (2 papers, 2020 to 2021). "In the following sections, we have summarized certain basic findings concerning VCP/p97 in cardiovascular diseases." (PMID 33439255, 2021). "This review summarizes current findings regarding VCP/p97 in the cardiovascular system for the first time, and discusses the role of VCP/p97 in cardiovascular disease." (PMID 33439255, 2021). "Another chaperone with significant implications in cardiovascular disease is p97/valosin-containing protein (VCP)/Cdc48, an ATPase involved in a variety of functions to include ERAD, cell cycle progression, autophagy, and DNA repair." (PMID 33281625, 2020). "Recent studies have shown that VCP/p97 may be a potential therapeutic target in cardiovascular diseases." (PMID 33439255, 2021).
hematological malignancies (2 papers, 2019 to 2024). "BET protein inhibitors including I-BET762, CPI-0610, and TEN-010, as well as the Kub reader p97/VCP inhibitor CB-5083, are in clinical trials for several solid tumors and hematological malignancies." (PMID 38862432, 2024).
inflammation (1 paper, 2022). Aberrant reaction of the microcirculation characterized by movement of fluid and leukocytes from the blood into extravascular tissues. "Functional studies show that VCP controlled ER stress induces inflammatory responses in a NOD2-dependent fashion; thus, providing a new potential mechanistic link and therapeutic target in NOD2-related intestinal inflammation." (PMID 35273242, 2022).
VCP also shares sentences with these, for which no sentence is quoted: genetic disorders (7 papers); corticobasal degeneration (3); Lewy Body disease (3); acute coronary syndrome (2); colorectal tumors (2); endometrial cancer (2); myelodysplastic syndrome (2); non-Hodgkin lymphoma (2); pancreatic ductal adenocarcinoma (2); retinitis pigmentosa (2); sporadic amyotrophic lateral sclerosis (2); squamous cell carcinoma (2); acute myocardial infarction (1); Adult onset (1); atherosclerosis (1); autism spectrum disorder (1); autoimmune liver diseases (1); bladder tumor (1); brain diseases (1); Burkitt lymphoma (1); carcinoma in situ (1); cataract (1); cervical tumors (1); choriocarcinoma (1); chronic obstructive pulmonary disease (1); ciliopathies (1); clear cell sarcoma (1); colorectal adenoma (1); cutaneous T cell lymphoma (1); Danon disease (1).